ALK (ALK receptor tyrosine kinase)
Diseases named in the same sentence as ALK in open-access papers (continued):
Sharing a sentence is not in itself a finding about the gene and the disease.
anaplastic large cell lymphoma (continued). "Results summary of pathological and genomic testing for the diagnosis of this case of ALK-positive anaplastic large-cell lymphoma." (PMID 40161372, 2025). "In anaplastic large cell lymphoma (ALCL) positive for anaplastic lymphoma kinase (ALK+), the aberrant overexpression of TIMP1 is directly associated with persistent STAT3 phosphorylation, thereby accelerating tumor progression." (PMID 41189944, 2025). "Another study showed that in ALK (−) anaplastic large cell lymphoma (ALCL) tumor cells as well as B cells, natural killer/T cells, T cells, and classical Hodgkin lymphoma, only MCT1 is widely expressed." (PMID 39464313, 2024). "For example, in ALK+ anaplastic large cell lymphoma, NPM-ALK activates downstream MEK-ERK and STAT3 pathways to promote PD-L1 expression." (PMID 38762484, 2024). "Miscellaneous rare lymphomas that can primarily occur in the CNS are MALT lymphoma of the dura, other low-grade B-cell lymphomas of the CNS, anaplastic large cell lymphoma (ALK + /ALK −) and T-cell and NK/T-cell lymphomas." (PMID 38858236, 2024). "ALK was initially identified as a component of a fusion protein in anaplastic large cell lymphomas, which led to its designation as a specific kinase." (PMID 39594806, 2024). "Amplification of ALK has been detected in neuroblastoma breast cancer, anaplastic large cell lymphoma and pulmonary sarcomatoid carcinoma." (PMID 38953007, 2024). "Except for Anaplastic Lymphoma Kinase (ALK) positive anaplastic large cell lymphoma (ALCL), patients with PTCL generally have a poor prognosis." (PMID 39041683, 2024). "A recent study confirmed the prognostic value of MRD in anaplastic lymphoma kinase (ALK)-positive anaplastic large-cell lymphoma (ALCL)." (PMID 39188727, 2024). "In anaplastic large cell lymphoma, the frequency of ALK fusions is approximately 50–80%, with a similar prevalence observed in inflammatory myofibroblastic tumors at around 50–60%." (PMID 39594806, 2024). "Anaplastic lymphoma kinase (ALK) is a receptor tyrosine kinase identified in cells of anaplastic large-cell lymphoma." (PMID 39728071, 2024). "The identification of anaplastic lymphoma kinase (ALK) emerged initially within a subset of anaplastic large-cell lymphomas back in 1994." (PMID 39001519, 2024). "PTP1B and PTPN2, pivotal phosphatases for ALK, play a crucial role in determining the responsiveness to ALK TKIs in anaplastic large-cell lymphomas through their regulatory actions on ALK and SHP2 phosphorylation levels." (PMID 39065585, 2024). "Anaplastic lymphoma kinase (ALK) is a receptor tyrosine kinase discovered in anaplastic large-cell lymphoma cells." (PMID 38254833, 2024). "Other differential diagnoses include chronic inflammation, vascular-type fibrous histiocytoma, ALK-positive large B-cell lymphoma, and ALK-positive anaplastic large-cell lymphoma." (PMID 38706599, 2024). "Additional ALK-positive/altered tumors that have been previously localized within the posterior fossa, include anaplastic large-cell lymphomas, IMT, and intracranial mesenchymal tumors that are FET::CREB-fusion-positive." (PMID 38339401, 2024). "One patient (1/18, 5.5%) had a fusion that refined diagnosis from anaplastic large cell lymphoma (ALCL) to ALK-fusion positive ALCL (IGMCH0009)." (PMID 39687881, 2024). "The ALK gene (anaplastic lymphoma kinase) was discovered as a result of genetic studies in anaplastic large cell lymphoma." (PMID 38953007, 2024). "Upregulation of PTPN11 phosphatases have been reported to mediate resistance to ALK-TKI in ALK+ anaplastic large cell lymphoma and in a variety of other cancers." (PMID 39695132, 2024). "When RDD presents in the cranial bones, careful differentiation is required from conditions such as Langerhans Cell Histiocytosis, ALK-positive histiocytosis, Anaplastic Large Cell Lymphoma, and metastatic tumors." (PMID 38903706, 2024).
anaplastic large cell lymphoma (continued). "A previous study reported a 23-year-old female patient with ALK+ LBCL who was misdiagnosed with anaplastic large cell lymphoma due to a diffuse expression of CD30." (PMID 39906668, 2024). "Rearrangement of the DUSP22 gene is also seen in a subset of systemic ALK-negative anaplastic large cell lymphoma (ALK-ALCL) and in about 20% of pcALCL." (PMID 36278991, 2023). "The pathological diagnosis of the biopsied specimen proved to be the common type of ALK‐positive anaplastic large cell lymphoma (ALCL)." (PMID 36794043, 2023). "The initial characterization of rearrangements involving the anaplastic lymphoma kinase (ALK+)-activating gene occurred in individuals diagnosed with anaplastic large cell lymphoma (ALCL)." (PMID 37896209, 2023). "The designation “ALK” stems from its identification as a crucial driver in anaplastic large-cell lymphoma (ALCL)." (PMID 37513921, 2023). "Among anaplastic large cell lymphomas (ALCLs), the separation of ALK-positive from ALK-negative tumors is required because the outcome of ALK-positive ALCL is generally superior to that of most ALK-negative ALCL subtypes." (PMID 38175372, 2023). "Significant PD-1 expression has been reported in the TME of many subtypes of PTCL such as Angioimmunoblastic T-Cell Lymphoma (AITL), PTLD-NOS, and ALK- Anaplastic Large Cell Lymphoma (ALCL)." (PMID 37920162, 2023). "ALK-negative (ALK−) ALCL, which lacks the ALK protein and ALK rearrangement, represents a distinct subtype of anaplastic large-cell lymphoma." (PMID 37762472, 2023). "This has led some laboratories to validate and maintain a separate ALK stain using a high-sensitivity ALK protocol for use in solid tumors in addition to ALK01-based protocols for ALK-positive anaplastic large cell lymphoma." (PMID 38175372, 2023). "Based on a discussion with laboratory directors at other institutions, the ALK01 clone has been a commonly used antibody for the detection of ALK expression in ALK-positive anaplastic large-cell lymphoma." (PMID 38175372, 2023). "Anaplastic large-cell lymphoma (ALCL) ALK+, anaplastic large-cell lymphoma (ALCL) ALK−, and breast-implant-associated (BI) anaplastic large-cell lymphoma were all classed together in the ICC and the WHO-HAEM5." (PMID 37762472, 2023). "The two major subtypes of mature T cell NHL/leukaemia were peripheral T-cell lymphoma, not elsewhere classified (ICD-10: C844; ICD-O: 9720/3) 31/75 (41.3%) and anaplastic large cell lymphoma, ALK-positive (ICD-10: C846; ICD-O: 9714/3) 23 (30.7%)." (PMID 37337159, 2023). "The identification of anaplastic lymphoma kinase (ALK) was originally accomplished in anaplastic large cell lymphoma (ALCL), which explains its name." (PMID 37375228, 2023). "Anaplastic lymphoma kinase (ALK) was first detected in a subset of anaplastic large-cell lymphomas in 1994." (PMID 37232842, 2023). "Anaplastic large cell lymphoma with anaplastic lymphoma kinase gene translocations (ALK+ ALCL) is a mature T-cell lymphoma that primarily affects lymph nodes, but also gives rise to tumors in extranodal organs and occasional characteristic skin lesions." (PMID 35246138, 2022). "In paediatric anaplastic large cell lymphoma cells, expression of the oncogenic protein anaplastic lymphoma kinase (ALK) correlated with expression of higher levels of TWIST1." (PMID 35203300, 2022). "Nodal lymphomas include anaplastic lymphoma kinase (ALK)-positive anaplastic large cell lymphoma (ALCL); ALK-negative ALCL; angioimmunoblastic T-cell lymphoma (AITL); and peripheral T-cell lymphoma, not otherwise specified (PTCL-NOS)." (PMID 35267494, 2022). "Systemic ALK-positive anaplastic large cell lymphoma primarily develops in young individuals and exhibits a slightly higher incidence rate in males." (PMID 35406421, 2022). "Anaplastic lymphoma kinase (ALK) is a receptor tyrosine kinase that was originally identified as a rearranged gene in anaplastic large cell lymphoma." (PMID 36337169, 2022).
anaplastic large cell lymphoma (continued). "While STAT3 activation is induced by ALK fusion proteins in ALK-positive ALCL, it is induced by somatic mutations of STAT3 and JAK1 in 20% of ALK-negative anaplastic large cell lymphomas and 5% of primary cutaneous ALCL, whereas mutations in these genes have not been reported for CD30+ PTCL." (PMID 35330161, 2022). "Decitabine has shown antineoplastic activity in ALK+ anaplastic large cell lymphoma (ALCL) cell lines." (PMID 36671446, 2022). "In cases of adult and pediatric or adolescent non-Hodgkin’s lymphoma, ALK-positive anaplastic large cell lymphoma accounts for 1–3% and 10–20%, respectively." (PMID 35406421, 2022). "Anaplastic Lymphoma Kinase (ALK)-positive anaplastic large cell lymphoma (ALCL) is characterized by oncogenic chromosomal translocations involving the ALK gene localized on chromosome 2p23." (PMID 35406475, 2022). "Crizotinib treatment of ALK+ anaplastic large cell lymphoma induced autophagy as a survival response, and excessive autophagy was related to cell death." (PMID 35459209, 2022). "ALK rearrangements with other fusion partners have been described in various malignancies, such as anaplastic large-cell lymphoma (ALCL), non-small cell lung cancer (NSCLC), anaplastic thyroid carcinoma, and others." (PMID 35409355, 2022). "Disease defining recurrent chimeric gene fusions from translocations, such as NPM/ALK or DUSP22/FRA7H in anaplastic large cell lymphoma is uncommon in mature T-Cell lymphomas." (PMID 35330161, 2022). "ALK is a receptor tyrosine kinase first identified as a component of the nucleophosmin (NPM)-ALK fusion oncoprotein aberrantly expressed in anaplastic large cell lymphoma (ALCL)." (PMID 35954326, 2022). "The oncogenic pathways activated by the NPM-ALK chimeric kinase of ALK+ anaplastic large cell lymphoma (ALCL) are well characterized; however, the potential interactions of ALK signaling with the microenvironment are not yet known." (PMID 35740600, 2022). "For instance, response rates as high as 80–90% with ALK inhibitor therapy have been observed in the treatment of anaplastic large cell lymphomas which harbor ALK translocations." (PMID 35233056, 2022). "An 11‐year‐old girl with cervical node ALK+ anaplastic large cell lymphoma (ALCL) in remission for 3 years after chemotherapy complained of dull ache in the lower part of both legs just above the heels." (PMID 35845193, 2021). "ALK- anaplastic large cell lymphoma (ALK- ALCL) is a rare subtype of CD30+ large T-cell lymphoma that typically affects older adults and has a poor prognosis." (PMID 34572893, 2021). "Classical Hodgkin lymphoma (cHL) and anaplastic lymphoma kinase-positive, anaplastic large cell lymphoma (ALK+ ALCL) are B and T cell lymphomas respectively, which express the tumour necrosis factor receptor superfamily member, CD30." (PMID 33413671, 2021). "Herein, we present an autopsy case of a disseminated anaplastic lymphoma kinase (ALK)-positive anaplastic large cell lymphoma with a dominant mediastinal involvement." (PMID 33968818, 2021). "Here we investigated the impact of autophagy inhibition in a cancer of lymphoid origin, namely ALK-positive anaplastic large cell lymphoma (ALK + ALCL)." (PMID 33430343, 2021). "This includes the CD30-positive lymphomas, classical Hodgkin lymphoma (cHL) and anaplastic lymphoma kinase-positive, anaplastic large cell lymphoma (ALK+ ALCL) where AP-1 proteins perform a variety of pro-tumour functions." (PMID 33413671, 2021). "Meanwhile, in Anaplastic large cell lymphoma cells (ALK+ ALCL), a low expression of miR-181 is also observed." (PMID 33412518, 2021). "Morris and colleagues first discovered ALK in 1994 as a fusion protein with nucleophosmin (NPM) in anaplastic large cell lymphoma (ALCL), which is a non-Hodgkin lymphoma." (PMID 34769149, 2021).
anaplastic large cell lymphoma (continued). "Other case reports revealed that ALK-translocated inflammatory myofibroblastic tumors (IMT) and ALK-positive anaplastic large cell lymphoma (ALCL) showed encouraging response rates to crizotinib, including completely responding patients." (PMID 34832908, 2021). "ALK-positive anaplastic large cell lymphoma (ALK + ALCL) is a specific type of T-cell non-Hodgkin lymphoma affecting mostly children and young adults." (PMID 33430343, 2021). "Transplanting these into recipients lead to two cases of T lineage ALK+ anaplastic large-cell lymphoma and one case of anaplastic ALK+ large B-cell lymphoma." (PMID 34484175, 2021). "Other notable successes in pediatric solid tumors include targeting the ALK fusions observed in the majority of anaplastic large cell lymphoma (ALCL) and approximately half of the patients with inflammatory myofibroblastic tumors (IMT)." (PMID 34298746, 2021). "It is currently in development for the treatment of advanced malignant solid tumor and relapsed or refractory ALK-positive anaplastic large cell lymphoma (ALCL)." (PMID 35115931, 2021). "First identified in anaplastic large cell lymphomas, ALK is a receptor protein tyrosine kinase that activates many downstream signaling pathways, resulting in increased cell proliferation and survival." (PMID 34530849, 2021). "In ALK + anaplastic large cell lymphoma, a strong correlation was found between the positive expression of p-Stat3 and the expression of Survivin." (PMID 34736477, 2021). "It exerts an oncogenic effect on ALK+ anaplastic large cell lymphoma by the alteration of the membrane lipid composition and inhibition of ferroptosis." (PMID 33989111, 2021). "ALK+ anaplastic large cell lymphoma (ALCL) cell lines and primary tumors which are less of SQLE expression are highly dependent on cholesterol uptake." (PMID 33791309, 2021). "Anaplastic lymphoma kinase-positive (ALK+) anaplastic large-cell lymphoma (ALCL) is a subtype of non-Hodgkin lymphoma characterized by expression of the oncogenic NPM/ALK fusion protein." (PMID 34503232, 2021). "In children with ALK-positive anaplastic large cell lymphoma, MDD and MRD detected in the blood or bone marrow is associated with high relapse risk." (PMID 33921029, 2021). "ALK-positive anaplastic large cell lymphoma (ALK + ALCL) is a distinct type of non-Hodgkin lymphoma of T-cell lineage occurring most frequently in young adults and children." (PMID 34287231, 2021). "We present a case of a 35-year-old male with a nasopharyngeal mass and cervical lymphadenopathy and the adversities faced by out otolaryngology department with obtaining the diagnosis of ALK-positive anaplastic large cell lymphoma." (PMID 34760325, 2021). "ALK +ve large cell lymphoma appears similar to Hodgkin’s lymphoma in that it has undergone V[D]J recombination but failed to produce a functional T cell receptor." (PMID 32582272, 2020). "ICD-0-3 and WHO classification codes were equal for the ALK-positive, primary cutaneous and the T and null cell type anaplastic large cell lymphomas." (PMID 32344893, 2020). "An EEF1G– anaplastic lymphoma kinase (ALK) gene fusion was recently found in two pediatric patients with anaplastic large cell lymphoma." (PMID 32328499, 2020). "In contrast to systemic anaplastic large-cell lymphoma (sALCL), the cases of ALK+ pcALCL seem to have a favorable outcome, comparable to that of patients with ALK- pcALCL." (PMID 32013101, 2020). "Potent CAR-T therapies that target appropriate antigens can benefit the treatment of anaplastic lymphoma kinase-positive (ALK+) anaplastic large cell lymphoma (ALCL), which is the most common subtype of T cell lymphoma." (PMID 33348781, 2020). "For patients treated with CHOP-like regimen, the overall response rate is about 50% and the long-term outcome remains poor, with a 3-year event-free survival (EFS) below 50% for PTCL, except for ALK+ anaplastic large cell lymphoma (ALCL)." (PMID 32429979, 2020).
anaplastic large cell lymphoma (continued). "Amongst the malignancies arising later in the T cell developmental pathway ALK +ve anaplastic large cell lymphoma also has a high chemotherapy cure rate with long term survival rates of up to 80% are reported." (PMID 32582272, 2020). "Except for ALK + anaplastic large-cell lymphoma (ALCL), most peripheral T-cell lymphomas are highly malignant and have an aggressive disease course and poor clinical outcomes, with a poor remission rate and frequent relapse after first-line treatment." (PMID 33160401, 2020). "IGF-IR interacts with NPM-ALK and then promotes T cell ALK+ anaplastic large cell lymphoma cells survival." (PMID 32493414, 2020). "Crizotinib, a small-molecule kinase inhibitor, which was intended to treat ALK-positive anaplastic large-cell lymphoma, is now repositioned to treat this small subset of NSCLC." (PMID 32972027, 2020). "Anaplastic lymphoma kinase (ALK) gene, first discovered in a subtype of anaplastic large cell lymphoma, is responsible for encoding a receptor tyrosine kinase (RTK) called ALK." (PMID 33292625, 2020). "The role of ALK genetic aberrations in human carcinogenesis was widely recognized upon discovery of the nucleophosmin (NPM)-ALK gene fusion in anaplastic large cell lymphoma (ALCL) in 1994." (PMID 32059449, 2020). "Recently, it was found that ALK+ anaplastic large cell lymphoma (ALCL) cells (a rare type of lymphoma) were unable to thrive in an environment that lacks cholesterol." (PMID 32577155, 2020). "Differential diagnoses comprise an anaplastic lymphoma kinase-(ALK)-positive anaplastic large cell lymphoma; however, immunophenotypic negativity for ALK argues against this entity." (PMID 32845352, 2020). "It comprises a set of disorders that includes peripheral T-cell lymphoma not otherwise specified (PTCL-NOS), angioimmunoblastic T-cell lymphoma (AITL), anaplastic lymphoma kinase (ALK-) positive and ALK-negative forms of anaplastic large cell lymphoma (ALCL), and enteropathy-associated TCL2." (PMID 32317694, 2020). "Among the 10 lymphoma patients, 8 (80%) were diagnosed with diffuse large B-cell lymphoma, while 1 (10%) was diagnosed with ALK (+) anaplastic large cell lymphoma, and 1 (10%) was diagnosed with Hodgkin's lymphoma." (PMID 32788869, 2020). "Among those, miR-93 has shown to be overexpressed in several malignancies including ALK + anaplastic large cell lymphoma (ALCL), gastric as well as hepatocellular carcinomas." (PMID 31648231, 2019). "Anaplastic lymphoma kinase (ALK) was initially described as a fusion partner of nucleophosmin (NPM) in the NPM-ALK translocation in a cell line derived from a patient with anaplastic large cell lymphoma (ALCL)." (PMID 31334113, 2019). "Anaplastic lymphoma kinase (ALK) fusions were first noted in a subset of anaplastic large cell lymphoma with translocations involving ALK on chromosome 2p and molecular partners such as NPM-ALK, TPM3-ALK, and TFG-ALK." (PMID 30886831, 2019). "Anaplastic lymphoma kinase (ALK) translocation was first reported in a distinct subset of anaplastic large cell lymphoma, which is a rare subtype of T-cell lymphoma." (PMID 31627758, 2019). "The oncogenic fusion protein of anaplastic lymphoma kinase (ALK) with nucleophosmin 1 (NPM1) in anaplastic large cell lymphoma leads to the activation of multiple intracellular signal transduction pathways including PI3K–AKT, MAPK/ERK, mTOR, STAT3, and STAT5B." (PMID 31690038, 2019). "As an exception, STAT1 was shown to be an oncogenic driver in T-cell acute lymphoblastic leukemia (T-ALL) and ALK+ anaplastic large cell lymphoma (ALCL), and STAT1 is associated with the JAK2 exon 12 mutation in the progression of myeloproliferative neoplasms (MPNs)." (PMID 31817042, 2019). "Six patients with anaplastic large cell lymphoma, ALK positive were excluded in the following statistical analysis for their unique pathological types and good prognosis." (PMID 31737117, 2019).